MCM7 (minichromosome maintenance complex component 7)
Description:
Acts as a component of the MCM2-7 complex (MCM complex) which is the replicative helicase essential for 'once per cell cycle' DNA replication initiation and elongation in eukaryotic cells. Core component of CDC45-MCM-GINS (CMG) helicase, the molecular machine that unwinds template DNA during replication, and around which the replisome is built. The active ATPase sites in the MCM2-7 ring are formed through the interaction surfaces of two neighboring subunits such that a critical structure of a conserved arginine finger motif is provided in trans relative to the ATP-binding site of the Walker A box of the adjacent subunit. The six ATPase active sites, however, are likely to contribute differentially to the complex helicase activity. Required for S-phase checkpoint activation upon UV-induced damage.
Synonyms: CDC47; MCM2; PPP1R104; P1.1-MCM3; P1CDC47; P85MCM; PNAS146
Tractability: Small molecule: a structure with a bound ligand is known. PROTAC: UniProt records ubiquitination sites on it; ubiquitination databases record sites on it; its protein half-life has been measured.
Target class: Enzyme; Hydrolase
Gene: Protein-coding gene on chromosome 7 (100,092,233 to 100,101,940, reverse strand). Ensembl gene ENSG00000166508.
Subcellular location: Nucleus; Chromosome
Subcellular location (Human Protein Atlas): Nucleoplasm; Basal body; Cytosol
Pathways (Reactome):
DNA Replication: Activation of the pre-replicative complex; Assembly of the pre-replicative complex; Orc1 removal from chromatin; Switching of origins to a post-replicative state; Unwinding of DNA
Cell Cycle: Activation of ATR in response to replication stress
Gene Ontology:
Molecular function: ATP hydrolysis activity; DNA helicase activity; protein binding; single-stranded DNA binding; DNA binding; single-stranded DNA helicase activity; ATP binding
Biological process: DNA damage response; DNA replication; regulation of phosphorylation; DNA replication initiation; DNA strand elongation involved in DNA replication; double-strand break repair via break-induced replication; regulation of DNA-templated DNA replication initiation; cellular response to epidermal growth factor stimulus; DNA metabolic process; response to xenobiotic stimulus
Cellular component: chromosome, telomeric region; CMG complex; MCM complex; membrane; nucleolus; nucleus; chromatin; nucleoplasm; chromosome
Genetic constraint (gnomAD): Loss-of-function variants: 95 observed, 86.31 expected, observed/expected ratio (o/e) 1.1, 90% interval 0.93 to 1.3. The synonymous counts are far from expectation, so gnomAD's model fits this gene poorly and the ratio says little. Missense variants: 1,087 observed, 1,000.8 expected, observed/expected ratio (o/e) 1.09, 90% interval 1.03 to 1.14. Synonymous variants: 461 observed, 369.05 expected, observed/expected ratio (o/e) 1.25, 90% interval 1.16 to 1.35.
Homologues: Orthologues: chimpanzee MCM7 (99% identical), macaque MCM7 (98% identical), pig MCM7 (97% identical), rabbit MCM7 (97% identical), dog MCM7 (96% identical), guinea pig MCM7 (96% identical), rat Mcm7 (94% identical), mouse Mcm7 (93% identical), tropical clawed frog mcm7 (84% identical), Drosophila melanogaster Mcm7 (67% identical), zebrafish mcm7 (62% identical), Caenorhabditis elegans mcm-7 (50% identical). Paralogues in human: MCM3 (32% identical), MCM2 (31% identical), MCM6 (31% identical), MCM4 (30% identical), MCM9 (29% identical), MCM5 (29% identical), MCM8 (26% identical), MCMDC2 (14% identical).
Diseases named in the same sentence as MCM7 in open-access papers:
MCM7 is named in the same sentence as 132 diseases in open-access papers, as found by Europe PMC text mining. Sharing a sentence is not in itself a finding about the gene and the disease. The quoted sentences say what the papers report.
prostate carcinoma (23 papers, 2010 to 2025). A carcinoma that arises from epithelial cells of the prostate gland. "For example, the variant allele of rs2070215 increased the expression level of MCM7 in T cell leukemia cell line and prostate cancer, resulting in increased cell proliferation and relapse of prostate cancer." (PMID 31936215, 2020). "There are other pre-RC components, such as Orc2, Cdt1, and Mcm7, that are also reported to be associated with AR in prostate cancer cells." (PMID 23437213, 2013). "MCM7 has been linked to prostate cancer in particular and esophageal squamous cell carcinomas." (PMID 35428183, 2022). "Here we confirmed that MCM7 could be a survival predictor for prostate cancer, considering that a shorter disease-free interval was associated with higher MCM7 and other key proliferation factors expression." (PMID 34573332, 2021). "As overexpression of MCM7 has been associated with poor prognosis in prostate cancer and EMC, we hypothesized that the oncogenicity of MCM7 may be linked, at least in part, to overexpression of the hosted miRNAs." (PMID 23028803, 2012). "The analysis of a TCGA database revealed that the overexpression of NAT10, CDC6, and MCM7 in prostate cancers were correlated with the Gleason score and node metastasis." (PMID 35743017, 2022). "The results revealed that expression levels of NAT10 and Ki67, CDC6, and MCM7 were increased in prostate cancers." (PMID 35743017, 2022). "It has been reported that MCM7 is highly expressed in hepatocellular carcinoma, prostate cancer, esophageal cancer, lung cancer, etc.." (PMID 35494047, 2022). "Expression of MCM2 and MCM7 are positively correlated with the Ki67 proliferation marker in prostate cancer, breast cancer, colon cancer, ovarian cancer, lung, and bladder cancer." (PMID 30937307, 2019). "While MCM6 was reported to be prognostic marker in a few malignancies, MCM7 is extensively studied in human prostate cancer tissues and is correlated with higher propensities for prostate cancer progression, invasion, and metastasis." (PMID 28424404, 2017). "Enterolactone produced by the metabolism of plant lignans by intestinal bacteria showed anti-proliferative effects in prostate cancer cell lines by repression of DNA licensing genes including MCM7 as well as the miR-106b-25 cluster, and overexpression of tumor suppressor gene PTEN." (PMID 29765562, 2018). "In addition, binding of TPA to PKC activates PKC and its binding to RACK1, which in turn triggers translocation of RACK1 from the nucleus to the cytoplasm, inactivation of MCM7, and disintegration of the DNA replication initiation complex in prostate cancer." (PMID 28465488, 2017). "High MCM7 protein levels were demonstrated to correlate with prostate cancer progression, poor prognosis of non-small cell lung cancer patients, recurrence of colorectal cancer, as well as distant metastases, high histological grade and poor prognosis is soft tissue sarcomas." (PMID 28432562, 2017). "Furthermore, some of the targets predicted by TaLasso for miR-1 were related to the cancers in MCC data: for instance, MCM7, related to prostate cancer progression and TAGLN2, a colorectal cancer biomarker." (PMID 22348024, 2012). "Diminishing expression of MCM7 might increase radiotherapy response in prostate cancer." (PMID 36776764, 2023). "It has been reported that MCM7 regulates the splicing of EGFR and PDGFR in human prostate cancer cells." (PMID 40789837, 2025). "Fusions of MCM7 have previously been reported in the SCAN‐B breast cancer cohort, as well as in ovarian and prostate cancer from the TCGA project." (PMID 35182081, 2022). "In prostate cancer miR-106b-5p, miR-93-5p and miR-25-3p were confirmed as potent regulators of PTEN, and acting in cooperation with MCM7 they were able to initiate prostate oncogenesis." (PMID 28432562, 2017). "Consistent with this line of evidence, we demonstrated that ORC6, DCD6, MCM7 together with PCNA and cyclin E were diminished in quiescent prostate cancer cells." (PMID 26416244, 2015).
prostate carcinoma (continued). "Notably, MCM7 has been reported to positively regulate the mRNA splicing of EGFR and PDGFR through its interaction with SF3B3 in prostate cancer, suggesting its significant role in the pathogenesis of liver fibrosis." (PMID 40789837, 2025). "Interestingly, this cluster lies within an intronic region of the minichromosome maintenance complex component 7 (MCM7) gene, which the authors found to be overexpressed in prostate cancer and to co-operate with the miR106b-25 cluster in tumour development." (PMID 25496077, 2014). "Notably, MCM7 has been found to bind to the SF3B3 subunit of the RNA splicing complex, thereby regulating the expression of fibrosis-related factor receptors EGFR and PDGFR at the splicing level in prostate cancer." (PMID 40789837, 2025).
lung cancer (22 papers, 2011 to 2025). A malignant neoplasm involving the lung. "MCM7 was associated with tumor development and progression in many cancers, including lung cancer." (PMID 34299042, 2021). "The data imply that expression levels of MCM7 in lung cancer tissues appear to be significantly higher than those in some MCM7-expressing normal tissues like gastrointestinal tissues." (PMID 21619671, 2011). "Moreover, increased levels of MCM7 or SHMT2 expression have been associated with poor prognosis in various cancers, including breast and lung cancers." (PMID 39435287, 2024). "On the other hand, MTL5 may positively regulate the expression of DNA replication licensing factors such as MCM5 and MCM7 in lung cancer." (PMID 35249447, 2022). "Thus, CCNE2 and MCM7 can be good indicators for cellular proliferation and prognosis in lung cancer." (PMID 32596300, 2020). "Intriguingly, quantitative real-time PCR showed that expression levels of MCM7 in 9 lung cancer tissues (6 NSCLC cases and 3 SCLC cases) were significantly higher than those in 11 normal tissues containing lung, brain, colon, esophagus, eye, liver, rectum, stomach, bladder and kidney." (PMID 21619671, 2011). "In this case, we quantitatively compared MCM7 expression levels in normal gastrointestinal tract tissues and lung cancer tissues, and the result showed that expression levels of MCM7 in lung cancer tissues are significantly higher than those in gastrointestinal tract normal tissues." (PMID 21619671, 2011). "Four other genes involved in the ceRNA network, including MCM7, NCAPG2, SETD6, and KIF22 have also been reported to involved in lung cancer progression." (PMID 37098483, 2023). "However, MCM7 may be a more sensitive marker than Ki67, as previously demonstrated in lung cancer." (PMID 35892846, 2022). "In summary, the high expression of the MCM7 and CCNE2 were significantly related with advanced tumors and worse OS in lung cancer." (PMID 32596300, 2020). "Transcriptomic alterations that occur during lung cancer development include over-expressed cell cycle related genes like E2F3, BUB3, CDK4, MCM2, MCM3, and MCM7 as summarized by Powell and Borczuk." (PMID 26930711, 2016). "MTHFD2 was involved in lung cancer cell proliferation, migration, and apoptosis by mediating its downstream molecules, such as DNA helicases (MCM4 and MCM7), as well as ZEB1, Vimentin and SNAI1, which contributed to tumor cell growth and epithelial-to-mesenchymal transition (EMT) process." (PMID 35790743, 2022). "Thus, the MCM7 and CCNE2 genes can be good indicators for cellular proliferation and prognosis in lung cancer." (PMID 32596300, 2020). "In lung cancer, high expression levels of MCM2, MCM5, MCM6, and MCM7 could be useful prognostic markers." (PMID 31514295, 2019). "For instance, MCM7 is a significant subunit of MCM complex, which could be a novel therapeutic target in lung cancer." (PMID 24643254, 2014). "The mechanisms responsible for the elevated levels of MCM in cervical cancers are not well described, but in lung cancer, YAP/TAZ expression has been cited for promoting the upregulation of MCM7 transcription leading to cell proliferation." (PMID 36016386, 2022).
hepatocellular carcinoma (18 papers, 2011 to 2025). A malignant tumor that arises from hepatocytes. "Furthermore, the higher expression of MCM7 was associated with poorer prognosis of the hepatocellular carcinoma patients and NSCLC patients than controls." (PMID 32596300, 2020). "High MCM7 expression was correlated with shorter overall survival in several cancers, including hepatocellular carcinoma, esophageal squamous cell carcinoma, and liver cancer, highlighting its potential as a prognostic and predictive biomarker." (PMID 40943553, 2025). "In hepatocellular carcinoma, increased expression of MCM7 correlated significantly with intrahepatic metastasis and vascular invasion." (PMID 37696392, 2024). "MCM7 inhibition led to a decrease in the esophagus and hepatocellular carcinomas viability, colony-forming ability, and migration capacity due to reducing phosphorylation of AKT1 and mTOR proteins with decreasing CDK1, CCNE1, and CCNE2 expression levels." (PMID 37529110, 2023). "A recent study shows that the histone deacetylase inhibitors (HDACi) SAHA epigenetically upregulates MICA expression through regulating the expression of miR-17-92 cluster and MCM7 in hepatoma." (PMID 32748943, 2020). "MCM7 is reported as a biomarker in human cancers such as hepatocellular carcinoma and lung cancer." (PMID 41145424, 2025). "Furthermore, miR‐214 targets overexpression of MCM5 and MCM7 in hepatocellular carcinoma (HCC) cells to inhibit cell replication and colony formation." (PMID 36776764, 2023). "And MCM7 was found to promote hepatocellular carcinoma through cyclin D1-dependent signaling." (PMID 37531195, 2023). "In the study of the mechanism of ATO killing hepatoma cells, the sequencing results of the researchers highly agree with our results, which indicated that MCM7 may play an important role in the antitumor effect of ATO." (PMID 34413873, 2021). "To investigate the potential oncogenic properties and prognostic value of MCM7 in hepatocellular carcinoma (HCC), we conducted immunohistochemistry staining of MCM7 in 153 HCC samples and found that MCM7 high expression level was associated with worse overall survival (OS) of HCC patients." (PMID 28182015, 2017). "Therefore, we investigated whether Mcm7 mRNA expression could be stimulated by S. mansoni egg antigens in human hepatoma cells." (PMID 37696392, 2024). "Genes, such as MCM3, MCM5, MCM7, and DSN1, are associated with the pathogenesis of various cancers, such as salivary gland cancer, cervical cancer, and hepatocellular carcinoma, through regulation of cell cycle, but these genes may be involved in progression of BRCA." (PMID 31311202, 2019). "Previous studies showed that MCM2 and MCM7 promote hepatocellular carcinoma cell stemness and tumor progression via hippo signaling and cyclin D1-dependent signaling, respectively, and overexpression of them correlates with poor prognosis in HCC." (PMID 38343446, 2023). "In hepatocellular carcinoma (HCC), the expression of the miR-106b precursor strongly correlates with MCM7 expression, indicating that the miR-106b-25 polycistron is coordinately transcribed under the influence of the MCM7 promoter." (PMID 21283757, 2011). "Previous research has shown that MCM7 promotes hepatocellular carcinoma (HCC) progression via the MCM7-cyclin D1 signaling pathway, suggesting its potential as a target for therapeutic intervention in hepatocellular carcinoma." (PMID 40789837, 2025). "Unfortunately, correlation analysis between MCM7 and CDC25B expression in hepatocellular carcinoma cell lines or clinical hepatocellular carcinoma tissues was not performed in this study to further validate the important role of MCM7 in the CDC25B-CDK1 axis." (PMID 39371450, 2024). "Furthermore, cell culture experiments showed that even isolated egg proteins alone are sufficient to induce expression of MCM7 in human hepatoma cells without the involvement of the generally accepted paracrine-triggered mechanism by mitogens such as interleukin 6 and EGF." (PMID 37696392, 2024).
breast carcinoma (15 papers, 2009 to 2025). "Decreased expression of RB and MCM7 create genome instability and thus induce apoptosis in simvastatin-treated mammary carcinoma mice xenografts." (PMID 36579200, 2022). "MCM7 was found to be a target of the Hippo pathway transcriptional coactivators YAP/TAZ by ChIP-seq in breast cancer cells." (PMID 31316723, 2019). "We also observed that simvastatin downregulated MCM7 and induced DNA damage in TamR breast cancer cells." (PMID 28150753, 2017). "For example, miRNA-convergent fusions involving the mir-21 host gene VMP1 were found in 4.3% of all breast cancer samples analyzed at the miRNA expression level, and in more than 3% for MCM7, host gene of the mir-25-106b cluster." (PMID 28983113, 2017). "A recent study indicated that high expression levels of CCNE2 would increase the combination with minichromosome maintenance protein MCM2 and MCM7 of the pre-replication complex, subsequently promoting genomic instability and cell proliferation in breast cancer." (PMID 36233194, 2022). "However, in the prognostic classifier for breast cancer, the weight of the well-studied MCM7 oncogene was essentially lower than the weight of the SMC4 gene with less reported oncogenic potential." (PMID 29402894, 2018). "In our study, we investigated the effects of simvastatin on tamoxifen-resistant breast cancer cells and determined that MCM7 downregulation may contribute to simvastatin’s effects." (PMID 28150753, 2017). "Therefore, a possible explanation for the role of EIF3B in regulating breast cancer might be that it affects the expression of MCM7 to block the G1/S transition of the breast cancer cell cycle and cell proliferation." (PMID 35040374, 2022). "Identification of molecular targets such as MCM7 and BRCA1 is important in elucidating the detailed mechanisms of statin therapy in breast cancer." (PMID 36579200, 2022). "Interestingly, the expression of MCM7 decreased after the knockdown of EIF3B expression, indicating that EIF3B might inhibit breast cancer cell growth by inhibiting the G1/S transition of the cell cycle." (PMID 35040374, 2022).